MYD88 (MYD88 innate immune signal transduction adaptor)
Diseases named in the same sentence as MYD88 in open-access papers (continued):
Sharing a sentence is not in itself a finding about the gene and the disease.
breast cancer (continued). "Furthermore, our data showed that the downregulation of MyD88 expression could significantly enhance PTX chemosensitivity in both breast cancer MCF-7 cells, lung cancer A549 cells, and ovarian cancer A2780 cells." (PMID 31259152, 2019). "Our results suggested that Chinese propolis and its major constituent – CAPE inhibited TLR4 signaling pathway molecules such as TLR4, MyD88, IRAK4, TRIF and NF- kB p65, which might be one of the major causes for Chinese propolis and CAPE to inhibit breast cancer cell proliferation and survive." (PMID 28950845, 2017). "Notably, CCL2 expression was found to be dependent on MyD88 in murine mammary carcinomas cells." (PMID 27312666, 2016). "Therefore, TLR4/MyD88 signaling molecules may be novel therapeutic targets in patients with breast cancer." (PMID 25299052, 2014). "The expression levels of MYD88, DAXX and ANXA5 were significantly upregulated in the control samples compared to breast cancer samples." (PMID 41357233, 2025). "In breast cancer, tumor-derived autophagosomes activate the TLR4‒MyD88 signaling pathway in ECs to upregulate PD-L1 expression, directly inhibiting T-cell function." (PMID 40521189, 2025). "Then, we developed a risk prognostic model based on expression levels of PIK3CA, SESN3, ANXA5, MYD88, DPP4, DAXX, and CRIP1 to predict clinical outcomes in patients with breast cancer." (PMID 41357233, 2025). "MyD88 expression levels relate to breast cancer TNM staging, being more detectable in stage III compared to stage I or II breast cancer patients." (PMID 38347830, 2024). "Activation of the TLR2/MyD88/NF-κB pathway elevates the autocrine secretion of VEGF and MMP9 in MDA-MB-231 cells, recognized as pivotal factors for breast cancer cell invasion and adhesion." (PMID 38347830, 2024). "Within breast cancer stem cells, the HMGB1/TLR2/MyD88 axis governs NF-κB activation, IL-6 and TGF-β production, and the activation of STAT3 and Smad3." (PMID 38347830, 2024). "Advanced glycation end products (AGEs) can promote breast cancer cell migration and invasion through the activation of the RAGE/TLR4/MyD88 signaling cascade." (PMID 38347830, 2024). "The MyD88 inhibitor TJ-M2010 interferes with the MyD88/PI3K/GSK-3β axis, consequently restraining breast cancer cell proliferation." (PMID 38347830, 2024). "Additionally, activation of the TLR2/MyD88 signaling pathway could activate NF-κB and Wnt signaling, participate in the pathogenesis of intracranial aneurysms, and induce the proliferation of colorectal cancer or breast cancer cells." (PMID 38785969, 2024). "Similarly, AGAP2-AS1 induces histone acetylation in the MYD88 promoter region, which stimulates cell proliferation and suppresses apoptosis in breast cancer (BC)." (PMID 38274897, 2023). "In breast cancer cells, IRF3 and MyD88 mRNAs were detected while IRF1 and IRF7 mRNAs were upregulated." (PMID 35737804, 2022). "In summary, LPS sensitizes the therapeutic response of both triple-negative and ER+ breast cancer to IAP antagonist therapy by inducing rapid apoptosis of the cancer cells through TLR4- and MyD88-mediated production of TNFα." (PMID 36119107, 2022). "In our previous research, we found that bacterial lipopolysaccharide (LPS) promoted the metastasis of breast cancer cells in vitro and in vivo by activating the TLR4/MyD88/NF-κB signaling pathway." (PMID 34475958, 2021). "This study addresses the TLR3 ligand-mediated signaling cascade that regulates a proliferative effect in breast cancer cells (MDA-MB-231 and T47D) challenged with TLR3 ligand in the presence of myeloid differentiation primary response 88 (MyD88) inhibitor." (PMID 33072559, 2020). "The results indicated that TLR4, MyD88 and p-NF-κB p65 were up-regulated in NMU-induced breast cancer, along with its downstream pro-inflammatory factors." (PMID 33363472, 2020).
breast cancer (continued). "The induction of breast cancer cell lines (MDA-MB-231 and T47D) with the TLR3 ligand induces cellular proliferation through an MyD88-dependent manner via induction of proinflammatory cytokine IL-6 and cyclin D1." (PMID 33072559, 2020). "The inhibition of TLR2 or its downstream targets CD14, MyD88, and IRAK1 can inhibit the proliferation of human breast cancer (BRCA) cells." (PMID 33138076, 2020). "It has also been proposed that MyD88 influences Ras-related cytoplasmic ERK1/2 levels, and that MyD88-dependent signaling enhances the expressions of genes that could contribute to breast cancer progression and genes previously associated with poor outcomes in breast cancer patients." (PMID 32422978, 2020). "Our previous studies have also found that the expression of MyD88 was increased in breast cancer tissues and that the sensitivity of breast cancer cells to PTX was significantly increased after the regulation of the MyD88 expression." (PMID 31259152, 2019). "In accordance to recently published data MDA-MB-435-Hyg human breast cancer cells and M13MDA435-1 and -3 hybrid cells exhibited comparable expression levels of TLR4, TLR9, TRIF, Myd88, and TRAF6." (PMID 27187369, 2016). "In the present study, we analyzed the expression of MyD88 and TLR4 in 205 cases of breast cancer and evaluated their correlation with the clinicopathological characteristics and prognoses of these patients." (PMID 25360699, 2014). "Our results identified that TLR4 and MyD88 was expressed in MCF-7 and MDA-MB-231 human breast cancer cells, and the expression of TLR4 and MyD88 in both cell lines was increased notably is response to LPS stimulation and reduced by antagonist eritoran." (PMID 25299052, 2014). "We then investigated the relationship between the expression levels of MyD88 and TLR4 in clinical breast cancer samples by immunohistochemical staining." (PMID 25360699, 2014). "A significant positive correlation was observed between MyD88 and TLR4 immunostaining in the tissue samples of the patients (p<0.001), which is consistent with the results obtained using breast cancer cells lines." (PMID 25360699, 2014). "Thus, MyD88 expression may be helpful for predicting the prognosis of breast cancer patients." (PMID 25360699, 2014). "Particularly in breast cancer, SP1-induced overexpression of lncRNA AGAP2-AS1 upregulates MyD88 expression and activates the NF-κB signaling pathway by binding to the transcriptional coactivator CBP, which promotes breast cancer growth and enhances trastuzumab resistance." (PMID 40384875, 2025). "However, the introduction of a MyD88 inhibitor disrupted the signal transduction of the TLR3-MyD88-NF-κB (p65)-IL6-Cyclin D1 pathway, leading to reduced breast cancer cell proliferation." (PMID 38347830, 2024). "TLR4 and MyD88 protein expression levels are positively correlated with axillary lymph node metastasis and histological grade, and the co-expression of TLR4 and MyD88 is also positively correlated with breast cancer cell metastasis." (PMID 38347830, 2024). "Activation of the TLR5/MyD88/NME3/NFκB signaling pathway enhances host immunity, enhances the clearance of tumor xenografts, and potentially augments the effectiveness of immunotherapy, prolonging survival in breast cancer patients." (PMID 38347830, 2024). "Additionally, the expression level of MyD88 alongside TLR4 was also found to be positively correlated with axillary lymph node metastasis and histological-grade breast cancer development." (PMID 37822929, 2023). "Furthermore, the reversal effect of UA in 231/PTX cell disappeared after overexpression of MyD88, suggesting that miR-149-5p negatively regulate the expression of MyD88 by binding to its 3’-UTR, thereby reversing drug resistance of breast cancer." (PMID 34722295, 2021).
breast cancer (continued). "Our findings showed verbascoside has anti-tumor activity against breast cancer cells by initiating apoptosis cascade followed by activating MyD88 pathway and reducing NF-κB at mRNA level with no toxic effect on normal cells." (PMID 34844644, 2021). "MyD88 is essential for stimulating resistance to paclitaxel, doxorubicin, and tamoxifen; however, its roles in the ICI-related resistance of breast cancer cells remain unclear." (PMID 33096896, 2020). "Analysis of members of the TLR4 signal transduction cascade revealed comparable expression levels of Myd88 and TRAF6 in MDA-MB-435-Hyg breast cancer cells and M13MDA435 hybrid cells, whereas in M13SV1-EGFP-Neo breast epithelial cells the expression levels of these proteins were much lower." (PMID 26863029, 2016). "Moreover, TLR4 and TLR9 as well as TRIF, Myd88 and TRAF6 expression levels of MDA-MB-435-Hyg breast cancer cells were comparable to M13MDA435-1 and -3 hybrid cells." (PMID 27187369, 2016). "Few studies have investigated MyD88, an important adaptor protein of TLR4, in breast cancer." (PMID 25360699, 2014). "In agreement with this study, we observed that elevated MAP1S levels were accompanied by degradation of MyD88 and attenuation of MyD88-dependent transcription factor activation, suggesting that MAP1S provides negative feedback regulation in the TLR5 signaling pathway of breast cancer cells." (PMID 24466264, 2014). "Mechanistically, SLC12A8 activated the TLR signaling pathway (upregulating TLR2, MyD88, IRAK1, TAK1 in CD8+ T cells), leading to increased PD-1 expression on CD8+ T cells, resulting in their functional exhaustion and enhanced invasive ability of Luminal B breast cancer cells." (PMID 41795804, 2026). "Notably, MyD88 protein expression in breast cancer tissue surpasses that in adjacent non-cancerous tissue, and it is positively associated with axillary lymph node metastasis, histological grade, and distant metastasis." (PMID 38347830, 2024). "Moreover, subsequent research showed a higher protein level of Myd88 and TLR4 in breast carcinoma than paracarcinoma tissue, as well as a correlation between their expression and axillary lymph node metastasis that providing the metastatic potential role of TLR4/Myd88 signaling in breast cancer." (PMID 33669782, 2021). "Moreover we recently showed a cell-intrinsic role for the TLR2/MyD88 pathway in breast and colon epithelial stem/progenitor cell populations, and similar to what we describe here in HNSCC, the inhibition of the TLR2 signaling pathway in breast cancer resulted significant growth inhibition." (PMID 25846753, 2015). "However, the biological function of MyD88 in breast cancer has not been well defined." (PMID 25360699, 2014). "In contrast, breast cancer CD44+/CD24−/low CIC have dysregulated innate immune responses featuring dysfunctional virus recognition caused by impaired trafficking of TLR9 and cofactor MyD88 and the absence of TLR2, having a deleterious impact on TLR pattern recognition receptor signaling." (PMID 21079774, 2010). "A high level of MyD88 and TLR4 protein expression was confirmed in the hormone-resistant breast cancer cell lines MDA-MB-231, MDA-MB-231HM, and MDA-MB-468 but not in the MCF-7 and SKBR3 cell lines." (PMID 25360699, 2014). "In conclusion, non-CIC breast cancer cells feature oncolytic adenovirus recognition by TLR9 and TLR2 and intact TLR trafficking, whereas CIC have defects in trafficking of TLR9 and co-factor MyD88 and lack of TLR2." (PMID 21079774, 2010).
lupus (64 papers, 2008 to 2026). "On the other hand, Lyn-deficient mice were shown to develop lupus-like autoimmunity and nephritis in a dendritic cell MyD88-dependent manner, indicating that TLR-dependent hyperinflammation can trigger secondary autoimmunity." (PMID 33737335, 2021). "MyD88 forms oligomeric complexes with members of the IL-1 receptor-associated kinases (IRAKs), termed the Myddosome, and lupus in ABIN1[D485N] mice is also prevented by crossing to mice in which IRAK4 or IRAK1 are replaced by kinase-inactive mutants." (PMID 31694920, 2019). "In lupus-prone B6/lpr mice that have abnormalities in lymphoproliferation and lymphocyte differentiation, AS development is suppressed by Myd88 deficiency and this is accompanied by a remarkable suppression in lymphocyte abnormalities." (PMID 30250175, 2018). "Here, we determined the potent suppressive effects of Myd88 deficiency on AS development in lupus-prone B6/lpr mice, which have lymphoproliferation abnormalities, and also in NOD mice, which have no lymphoproliferation abnormalities." (PMID 30250175, 2018). "Interestingly, although TLR9 promotes loss of tolerance to DNA in lupus, it is protective against systemic lupus erythematosus through MyD88-independent roles." (PMID 40924473, 2025). "Likewise, B cell depletion of MyD88 results in abrogation of pathogenic autoantibody responses and is associated with the ES-62-induction of Bregs in mouse models of systemic lupus erythematosus, asthma and RA." (PMID 36105811, 2022). "In addition, germinal center formation and anti-nuclear antibody production requires MyD88-mediated signaling in B cells and DCs in lupus-prone Lyn-deficient mice." (PMID 30250175, 2018). "Thus, in a lupus-prone AS model that has severe lymphoproliferation, Myd88 deficiency shows a remarkable suppressive effect on AS development, which is due to a reduction in lymphoproliferation and regulation of lymphocyte differentiation." (PMID 30250175, 2018). "Furthermore, TLR9 and MyD88 signaling have been linked to class switching to pathogenic IgG2a and 2b auto-antibodies in lupus." (PMID 19094215, 2008). "TLR signaling was crucial for ABC differentiation as MyD88 ablation blocked ABC differentiation and rescued the subsequent drawbacks in Ship-deficient lupus mice." (PMID 39960645, 2025). "The role of TLR9 signaling is MyD88-independent in lupus, while the MyD88-mediated proinflammatory signaling promotes disease." (PMID 39960645, 2025). "In systemic lupus erythematosus (SLE, lupus), endosomal toll like receptors (TLRs), TLR7 and TLR9, that sense (self) RNA and DNA, respectively, by signaling via activation of MyD88, initiate the loss of self tolerance and control disease severity." (PMID 40794441, 2025). "Our study shows for the first time the dysregulation of redox homeostasis and apoptosis markers in brain tissue with concomitant activation of the TLR7/MyD88 pathway in an imiquimod-induced lupus model." (PMID 39061948, 2024). "MyD88 deficiency in NOD mice, as well as in lupus-prone B6/lpr mice that also develop spontaneous autoimmune sialadenitis, leads to a clearly reduced SS pathology, including lymphocytic infiltration and production of proinflammatory cytokines." (PMID 36389822, 2022). "In studies using DC depletion and DC plus B-cell Myd88 deletion, perivascular and peritubular infiltrates were decreased in DC-depleted and Myd88-deleted lupus-prone animals compared with sick control mice." (PMID 32818496, 2020). "Deficiency of the adaptor protein MyD88 ameliorates SLE specific autoantibodies and associated pathology in several lupus mouse strains." (PMID 31354738, 2019). "It has been shown that BAFF-induced lupus-like phenotypes are largely dependent on the TLR-associated signaling adaptor, MyD88." (PMID 30906792, 2019). "As is thought to occur in lupus, it is possible that MyD88-mediated signaling is important for B cells and DCs in AS development." (PMID 30250175, 2018).
lupus (continued). "Previous studies have shown that mice with B cell-specific MyD88 deletion have a significant reduction in GC formation upon stimulation with endogenous nucleic acid recognized by TLR 9 or 7 in a lupus-like autoimmune disease mouse model in Lyn−/− mice." (PMID 28316602, 2017). "The potential promise of crossing in MYD88L265P has been underlined by a recent study showing that autoantibody production in transgenic mouse models of human systemic lupus erythematosus (SLE) depends on MYD88." (PMID 24106612, 2013). "As expected, MyD88 protein expression was significantly enhanced in lupus mice." (PMID 41511304, 2025). "However, recent reports have demonstrated that lupus can develop independently of GCs in mouse models in which disease is dependent on MyD88 signalling." (PMID 35477763, 2022). "In line with our findings, it has been reported that MyD88 signaling is central in the formation of HEV in the ELS of the SMG and the development of autoimmune sialadenitis in two mouse models of associated SS, the lupus prone B6/lpr and the diabetic NOD mice." (PMID 34108972, 2021). "We found that every facet of the lupus phenotype could be prevented by crossing ABIN1[D485N] mice to MyD88 KO mice or to mice expressing kinase-inactive mutants of IRAK4 or IRAK1." (PMID 31615747, 2020). "Previous reports have shown that deletion of MyD88 can prevent lupus manifestations in mice." (PMID 30250175, 2018). "SLC15A4-, MyD88-, IRF8-, or IRF5-deficient lupus-prone mice have shown ameliorated lupus symptoms with reduced IFNα protein level in the serum, decreased IFNα transcript level in pDC, downregulation of type I IFN inducible genes, and suppressed activation of both T cells and B cells." (PMID 27034965, 2016). "When combining with the depletion of MyD88 in CD19 cre-Lyn deficient mice, the phenotypes of plasma cell differentiation and lupus nephritis are reversed, suggesting that Lyn play an inhibitory role in MyD88-mediated autoreactive B cell generation in lupus-prone mice." (PMID 26068236, 2015). "In contrast to the central role of MyD88 in the signaling process, only promising in vitro results are available for the MyD88 inhibitor, TJ-M2010-5, which was able to reduce the activation of lupus-like B cells by preventing proliferation and antibody production." (PMID 41573545, 2025). "Remarkably, these lupus-like phenotypes were reversed when the mice were crossed with MyD88-knockout mice, highlighting the essential role of TLR7-MyD88 signaling in lupus development." (PMID 40495154, 2025). "In imiquimod-induced lupus mouse model, imiquimod activated TLR7 receptor, activating downstream MyD88 and TRAF6, and releasing mitochondrial dsDNA and dsRNA through MyD88 and TRAF6 to further activate of MDA5 and cGAS pathways in splenic B cells." (PMID 39917309, 2025). "More importantly, the expression of MyD88 protein, a key adaptor in the TLR7 signaling pathway, was significantly enhanced in lupus mice compared to sham mice." (PMID 39061948, 2024). "We establish the importance of TLR7 and guanosine-containing self-ligands for human lupus pathogenesis, which paves the way for therapeutic TLR7 or MyD88 inhibition." (PMID 35477763, 2022). "Both TLR and IL-1R family members drive MyD88-dependent inflammation, and TLR7 is a MyD88-dependent endosomal TLR that has been shown to be of critical importance in several autoimmune diseases, most notably Systemic Lupus Erythematosus (SLE) or lupus." (PMID 36591307, 2022). "In other autoimmune diseases, Myd88 overexpression in dendritic cells (DCs) could result in systemic lupus erythematosus (SLE)-like disease." (PMID 35069523, 2021). "Elegant studies in lupus models revealed that recognition of endogenous nuclear antigens by B cell TLRs is necessary for autoantibody production in lupus and this facilitates the generation of ANA-secreting cells in a Myd88-dependent manner." (PMID 34381449, 2021).